EGFR (epidermal growth factor receptor)
Diseases named in the same sentence as EGFR in open-access papers (continued):
Sharing a sentence is not in itself a finding about the gene and the disease.
non-small cell lung carcinoma (continued). "The most common activating EGFR alterations in non-small cell lung carcinoma (NSCLC) are somatic in-frame deletions within exon 19 and the L858R missense mutation in exon 21, together comprising 80–90% of activating EGFR mutations." (PMID 38182677, 2024). "EGFR RTK inhibitors have been particularly successful in non-small cell lung cancer, but appeared ineffective when tested in GBM." (PMID 39062807, 2024). "Our results revealed unique mutation rates in the EGFR, KRAS, and ROS1 genes among non-small cell lung cancer patients." (PMID 38828424, 2024). "The aim of this study is to assess the impact of serum magnesium (Mg) levels on prognostic outcomes in patients with non-small cell lung cancer (NSCLC) undergoing treatment with epidermal growth factor receptor tyrosine kinase inhibitors (EGFR-TKI)." (PMID 39071492, 2024). "The identification and advancement of small-molecule inhibitors aimed at the EGFR have significantly transformed the therapeutic paradigm across multiple cancer types, notably within non-small-cell lung cancer (NSCLC)." (PMID 38611728, 2024). "Although our study primarily focuses on patients with EGFR-mutant non-small cell lung cancer treated with EGFR tyrosine kinase inhibitors, the potential of SAFE-MIL extends far beyond this specific context." (PMID 39211737, 2024). "EGFR is a desirable target in many illnesses such pancreatic cancer, breast cancer, and non-small cell lung cancer as well as those of the lung, ovarian, and breast regions." (PMID 38474579, 2024). "The Epidermal Growth Factor Receptor (EGFR) is considered an important target for anti-tumor therapy in many solid tumors such as non-small cell lung cancer, gastrointestinal cancer, and colorectal cancer." (PMID 39835140, 2024). "EGFR stimulation can lead to the synthesis of hsa_circ_0000190 (circCNIH4), an upregulated circRNA in non-small-cell lung cancer (NSCLC)." (PMID 38892280, 2024). "Third-generation EGFR tyrosine kinase inhibitors (TKIs), exemplified by osimertinib, have demonstrated promising clinical efficacy in the treatment of non-small cell lung cancer (NSCLC)." (PMID 39143065, 2024). "In the phase 2 APPLE trial, the utility of longitudinal plasma EGFR T790M monitoring for optimizing the sequencing of gefitinib and osimertinib in patients with advanced EGFR-mutant non-small-cell lung cancer was assessed." (PMID 38473302, 2024). "For example, in non-small-cell lung cancer (NSCLC), mutations in the structural domain of the epidermal growth factor receptor (EGFR) kinase render patients resistant to EGFR inhibitors such as gefitinib and erlotinib." (PMID 39065585, 2024). "These particles, which are typically found in vehicle exhaust and smoke from fossil fuels, are associated with non-small cell lung cancer (NSCLC) risk and drive mutations in EGFR and KRAS genes." (PMID 38473268, 2024). "Considering that over 60% of non-small cell lung carcinomas (NSCLCs) exhibit EGFR expression, it has emerged as a crucial target for cancer therapy." (PMID 39066355, 2024). "Cholesterol induces resistance to epidermal growth factor receptor tyrosine kinase inhibitors (EGFR-TKIs) in non-small cell lung cancer (NSCLC) via the EGFR/Src/Erk/SP1 signaling pathway 31, while elevated levels in lipid rafts induce gefitinib resistance." (PMID 38617549, 2024). "In a phase I clinical trial assessing the impact of CXCR5-modified CAR T cells targeting EGFR in advanced non-small cell lung carcinoma (NCT05060796), patients exhibited favorable tolerance to the treatment." (PMID 38903504, 2024). "EGFR mutations, ALK translocations, ROS1 aberrations and BRAF mutations are now routinely evaluated in advanced non-small cell lung cancer (NSCLC), especially in adenocarcinoma." (PMID 38200537, 2024). "Osimertinib is a chemotherapy drug which has been widely used for metastatic EGFR-mutant non-small-cell lung cancer treatment." (PMID 39588117, 2024).
non-small cell lung carcinoma (continued). "Recent studies using NGS shed more light on the actual impact of EGFR exon 19 deletion subtypes and VAF on clinical outcomes in EGFR-TKI-treated advanced non-small-cell lung cancer." (PMID 39063150, 2024). "Optimizing treatment for patients with EGFR Ex20Ins-mutant non-small cell lung cancer (NSCLC) presents a significant challenge, often requiring a delicate balance between efficacy and safety." (PMID 38910714, 2024). "EGFR alterations are observed in ~5% of all cancer patients, 14% of patients with non-small cell lung cancer, and 26% of patients with glioblastoma." (PMID 38548752, 2024). "The clinical efficacy of neoadjuvant immunotherapy plus chemotherapy remains elusive in localized epidermal growth factor receptor (EGFR)-mutant non-small cell lung cancer (NSCLC)." (PMID 38897205, 2024). "We have demonstrated here that the recalcitrant ERBB2 signal driving the EGFR T790M non-small cell lung cancer can be degraded by the engineered destabilized 3'UTR of ERBB2." (PMID 38699639, 2024). "By updating EGFR TKIs based on specific understanding of the receptor in non-small-cell lung cancer, new generations improve upon the last and lead to better treatment." (PMID 38396993, 2024). "Epidermal growth factor receptor (EGFR) exon 19 deletion is a major driver for the drug resistance of non-small cell lung cancer (NSCLC)." (PMID 38561419, 2024). "EGFR inhibitor and immunotherapy have been approved for adjuvant treatment in resectable non-small cell lung cancer (NSCLC)." (PMID 38347487, 2024). "EGFR mutation is the most common oncogenic change found in non-small cell lung cancers (NSLC) (including adenocarcinoma, squamous cell carcinoma, and large cell carcinoma), and anti-EGFR therapy is used in the treatment of NSLC." (PMID 38893257, 2024). "In a phase I trial, the combination therapy of crizotinib and erlotinib, an EGFR inhibitor, caused DED in some patients treated for advanced non-small-cell lung cancer." (PMID 38254833, 2024). "The third-generation EGFR-TKIs, such as osimertinib, aumolertinib, and furmonertinib, have been recommended as the preferred treatment for EGFR-mutant advanced non-small cell lung cancer (NSCLC)." (PMID 38440180, 2024). "Our recent work has revealed that pollution activated macrophages can drive non-small cell lung cancer initiation in an EGFR mutant mouse model, primarily via the pro-inflammatory cytokine IL1β (Research Square 10.21203/rs.3.rs-1770054/v1)." (PMID 36930945, 2023). "For example, CD82 directly associates with EGFR and suppressed EGF-induced lamellipodial extensions and cell migration in non-small cell lung cancer cells." (PMID 36941633, 2023). "In the present study, we showed that although PARP plus EGFR targeting led to more penetrant and durable responses in the non-small cell lung cancer (NSCLC) PDX model, it influenced the enrichment of stem-like cells and their relative proportion." (PMID 37441599, 2023). "Clinical studies suggest that immune checkpoint inhibitor (ICI) monotherapy has limited benefits in non-small cell lung cancer (NSCLC) patients after epidermal growth factor receptor-tyrosine kinase inhibitor (EGFR-TKI) failure." (PMID 37488517, 2023). "Afatinib was a covalent EGFR inhibitor that was used to treat metastatic non-small-cell lung cancer (NSCLC) with wild-type and L858R/T790M double mutations of EGFR." (PMID 37047004, 2023). "The effects of SFN in non-small cell lung cancer (NSCLC) seem to be related to the epidermal growth factor receptor (EGFR) status." (PMID 36776295, 2023). "It has been shown that the deregulation of the EGFR pathway leads to the acquisition of stem-like properties in non-small-cell lung cancer." (PMID 36675033, 2023). "With the development of precision diagnosis and treatment for non-small cell lung cancer (NSCLC), the epidermal growth factor receptor (EGFR) exon 20 insertion (ex20ins) mutations, as a rare subset of EGFR mutaions, have gradually attracted attention recently." (PMID 37316442, 2023).
non-small cell lung carcinoma (continued). "A meta-analysis reported similar observations when investigating EGFR and KRAS mutation status in matched primary tumors and distant metastasis of non-small cell lung cancer, which is also considered a tumor with a TMB." (PMID 38003476, 2023). "The aims of the study were to evaluate potential differences among first-line treatment for EGFR mutant (m+) non-small cell lung cancer (NSCLC) patients with brain metastasis in China and to identify the factors influencing survival outcomes." (PMID 36997925, 2023). "For example, EMT-TFs such as TWIST1 and ZEB1 have been reported to drive EMT-mediated resistance to EGFR inhibitors in EGFR-mutant non-small cell lung cancer." (PMID 36781842, 2023). "Binds to specific E.G.F.R. mutants (T790M, L858R, and exon 19 deletions), which are more prevalent in non-small cell lung cancer (N.S.C.L.C.) following the first-line EGFR-TKI treatment." (PMID 37259442, 2023). "One example within the targeted therapy class of systemic therapy is the TKI osimertinib, a third-generation agent for the treatment of epidermal growth factor receptor (EGFR) mutant non-small cell lung cancer (NSCLC)." (PMID 37373596, 2023). "Afatinib is a second-generation EGFR tyrosine kinase inhibitor recommended as the first-line treatment for patients with advanced EGFR mutant non-small cell lung cancer (NSCLC)." (PMID 37537219, 2023). "Aumolertinib, as a novel third-generation epidermal growth factor receptor tyrosine kinase inhibitor (EGFR-TKI), has been widely employed as a first-line treatment for advanced non-small cell lung cancer (NSCLC) patients with EGFR mutation." (PMID 38090500, 2023). "Minocycline is often administered prophylactically or therapeutically to non-small cell lung cancer (NSCLC) patients receiving epidermal growth factor receptor-tyrosine kinase inhibitors (EGFR-TKIs) for skin rash as an adverse event." (PMID 37221285, 2023). "The overexpression of EGFR was observed to be a causative agent of cancer progression first identified in squamous cell carcinomas (SCCs) and then in sarcomas, non-small cell lung carcinoma (NSCLC), and malignant gliomas." (PMID 38273823, 2023). "The role of EGFR in non-small cell lung cancer, glioblastoma, and basal-like breast cancer has inspired much research and drug development." (PMID 37587470, 2023). "Patients with non-small cell lung cancer (NSCLC) with EGFR exon 20 insertions are resistant to early generation EGFR tyrosine kinase inhibitors (TKI)." (PMID 37308490, 2023). "EGFR, a tyrosine kinase, is known to be involved in various cancers, including breast and non-small cell lung cancer, because of its proliferative and anti-apoptotic activities." (PMID 37629110, 2023). "EGFR is a receptor tyrosine kinase that is commonly upregulated in cancers such as in non-small-cell lung cancer, metastatic colorectal cancer, glioblastoma, head and neck cancer, pancreatic cancer, and breast cancer." (PMID 37210476, 2023). "In the context of non-small cell lung cancer (NSCLC) patients treated with EGFR tyrosine kinase inhibitors (TKIs), this research evaluated the prognostic value of CT-based radiomics." (PMID 37509204, 2023). "In an initial study, 11 patients with relapsed refractory non-small cell lung cancer (NSCLC) in which >50% tumour cells were EGFR+ were infused with up to 2.5 × 107 CAR T-cells/kg." (PMID 36829563, 2023). "The role of EGFR upregulation in tumor development and progression through the mechanism of tumor angiogenesis has been demonstrated in several tumors, for instance non-small-cell lung cancer, head and neck, pancreatic, colorectal, breast, and brain cancers." (PMID 37445908, 2023). "In non-small cell lung cancer, lovastatin combined with gefitinib produces a synergistic anti-tumor effect, reducing cancer cell proliferation by inhibiting the epidermal growth factor receptor." (PMID 36860321, 2023).
non-small cell lung carcinoma (continued). "AZD9291 is a third-generation EGFR inhibitor that has shown efficacy against non-small-cell lung cancer." (PMID 37936247, 2023). "We present a case of a woman with non-small-cell lung cancer (NSCLC) who experienced disease progression during treatment with the epidermal growth factor receptor (EGFR)-tyrosine kinase inhibitor (TKI) osimertinib due to an unplanned pregnancy." (PMID 37916176, 2023). "This meta-analysis reveals that the combination of erlotinib and bevacizumab can prolong progression-free survival but not overall survival compared to erlotinib alone in advanced EGFR-mutant non-small cell lung cancer." (PMID 37635242, 2023). "Gefitinib (GFT) is a selective epidermal growth factor receptor (EGFR) inhibitor clinically used for the treatment of patients with non-small cell lung cancer." (PMID 37351506, 2023). "As a standard therapy, tyrosine kinase inhibitors (TKIs) improved survival in patients with non-small cell lung cancer (NSCLC) and epidermal growth factor receptor (EGFR) mutation." (PMID 37139162, 2023). "Other bispecific antibodies include amivantamab, an EGFR/c-Met bispecific antibody for non-small-cell lung cancer (NSCLC) treatment, and tebentafusp, a novel gp100×CD3 for treatment of HLA-A*02:01 positive non-resectable or metastatic uveal melanoma." (PMID 37457707, 2023). "During the course of treating non-small cell lung cancer (NSCLC) with epithelial growth factor receptor (EGFR) mutant, gefitinib resistance (GR) is unavoidable." (PMID 37800802, 2023). "EGFR-based genetic testing has emerged as a key measure for targeted therapy in non-small cell lung cancer." (PMID 36701708, 2023). "Non-small cell lung cancers (NSCLC), over half of which carry EGFR mutations, are the leading cause of brain metastases." (PMID 37296975, 2023). "Clinical trials have reported benefits for non-small cell lung cancer patients with EGFR mutant tumours treated with the pan-ERBB inhibitor dacomitinib." (PMID 37558831, 2023). "We report a 37-year-old woman with advanced non-small cell lung cancer (NSCLC) harboring an exon 19 deletion of EGFR treated with afatinib." (PMID 37035182, 2023). "More clinical evidence is needed regarding the relative priority of treatments for brain metastases (BMs) from EGFR/ALK-negative/unselected non-small cell lung cancer (NSCLC)." (PMID 36820064, 2023). "first reported DTCs when treating epidermal growth factor receptor mutant non-small cell lung cancer PC9 cells with the tyrosine kinase inhibitor erlotinib induced the formation of DTCs after removing the drug." (PMID 37483492, 2023). "In a small case series of non-small-cell lung cancer patients with monoclonal concomitant EGFR and ALK alterations, ALK inhibitors appeared to be effective for patients with co-alterations, but our patient eventually progressed while on lorlatinib." (PMID 37835855, 2023). "Molecular targeted therapy has made great progress in the treatment of advanced epidermal growth factor receptor (EGFR) mutant non-small cell lung cancer (NSCLC)." (PMID 36070068, 2023). "TCGA database analysis demonstrated that TET2 and EGFR mutations, as well as PTEN-EGFR mutations, are mutually exclusive, respectively, in non-small cell lung cancer (NSCLC)." (PMID 37550284, 2023). "Treatment of non-small cell lung cancer is increasingly biomarker driven with multiple genomic alterations, including those in the epidermal growth factor receptor (EGFR) gene, that benefit from targeted therapies." (PMID 36927889, 2023). "Targeting L858R/T790M and L858R/T790M/C797S mutant EGFR is a critical challenge in developing EGFR tyrosine kinase inhibitors to overcome drug resistance in non-small cell lung cancer (NSCLC)." (PMID 37049777, 2023). "The first EGFR-TKIs to be approved by the FDA for the treatment of advanced non-small-cell lung cancer were gefitinib, afatinib, dacomitinib, erlotinib, and osimertinib." (PMID 36768973, 2023).
non-small cell lung carcinoma (continued). "Tyrosine kinase inhibitors (TKI) targeting the epidermal growth factor receptor (EGFR) have significantly prolonged survival in EGFR-mutant non-small cell lung cancer patients." (PMID 37174055, 2023). "In total, 315 patients with EGFR-positive non-small cell lung cancer treated with 1G, 2G, and 3G EGFR-TKIs were included in this study." (PMID 37957228, 2023). "In another study, the combination therapy of gatipotuzumab with the EGFR-targeting antibody tomuzotuximab showed some anti-tumor activity in heavily pretreated EGFR-positive non-small cell lung cancer (NSCLC) patients and colorectal cancer (CRC)." (PMID 37489369, 2023). "The potential clinical use of trtDNA was mainly investigated in patients with non- small- cell lung cancer (NSCLC), testing for alterations in EGFR, including the T790M mutation and KRAS." (PMID 37542343, 2023). "The prognostic value of cytokeratin 19 fragment (CYFRA 21 − 1) and Ki67 in advanced non-small cell lung cancer (NSCLC) patients with wild-type epidermal growth factor receptor (EGFR) remains to be explored." (PMID 37004004, 2023). "A similar correlation occurs with the use of epidermal growth factor receptor (EGFR) inhibitors in patients with non-small cell lung cancer and nivolumab or pembrolizumab in patients with melanoma." (PMID 37511017, 2023). "In the Phase III FLAURA study (NCT02296125), first-line osimertinib improved outcomes vs comparator EGFR-TKIs in EGFRm advanced non-small cell lung cancer." (PMID 36849494, 2023). "Patients with advanced non-small cell lung cancer (NSCLC) with epidermal growth factor receptor gene (EGFR) Exon 20 insertions (Exon20ins) at the second line and beyond (2L+) have an unmet need for new treatment." (PMID 38001589, 2023). "The team created and characterized 3D homotypic and heterotypic spheroid models using EGFR inhibitor (EGFRi)-sensitive or EGFRi-resistant non-small cell lung cancer (NSCLC) cells." (PMID 37533100, 2023). "In vivo, 9 induced tumorregression in an intracranial patient-derived xenograft (PDX) murinemodel suggesting it as a potential lead for the treatment of localizedand metastatic non-small-cell lung cancer (NSCLC) driven by activatingmutant bearing EGFR." (PMID 37934858, 2023). "Based on a prior report by Kim, it can exhibit an anti-cancer effect by inhibiting the epidermal growth factor receptor (EGFR) and Wnt/β-catenin signaling in non-small cell lung cancer cells." (PMID 37762016, 2023). "One study, for example, directly links a treatment-induced ‘senescence-like state’ to dormancy in the context of EGFR targeted therapy in EGFR-mutant non-small-cell lung cancer." (PMID 36598661, 2023). "Between 20 and 40% of non-small cell lung cancer (NSCLC) patients will develop BMs during the disease, especially for patients with EGFR-mutated adenocarcinoma." (PMID 37759881, 2023). "The emergence of epidermal growth factor receptor-tyrosine kinase inhibitors (EGFR-TKIs) revolutionized the treatment of advanced-stage non-small cell lung cancer (NSCLC)." (PMID 37189759, 2023). "Epidermal growth factor receptor (EGFR)-tyrosine kinase inhibitors (TKIs) represented by gefitinib and erlotinib are widely used in treating non-small cell lung cancer (NSCLC)." (PMID 36910653, 2023). "Erlotinib (Tarceva®, OSI-774, R1415, CP358774, NSC718781) is a reversible small molecule ATP-competing inhibitor of EGFR primarily used to treat non-small cell lung cancer (NSCLC)." (PMID 37760847, 2023). "Epidermal growth factor receptor (EGFR) is an important biomarker for non-small cell lung cancer (NSCLC)." (PMID 37438719, 2023). "Epidermal growth factor receptor-tyrosine kinase inhibitors (EGFR-TKIs) are commonly used in the treatment of advanced non-small cell lung cancer." (PMID 36705363, 2023).